NGFR (nerve growth factor receptor)
Diseases named in the same sentence as NGFR in open-access papers (continued):
Sharing a sentence is not in itself a finding about the gene and the disease.
keratoconus (1 paper, 2023). A degenerative, structural disorder of the eye, characterized by a cone-shaped protrusion of the cornea. "According to A. Lambiase, the molecular basis of keratoconus is the complete absence of NGF TrkA receptor (TrkA NGFR) expression and decreased NGF and p75 NTR expression, which consequently cause the dysregulation of the NGF secretion pathway, resulting in reduced NGF secretion." (PMID 38203537, 2023).
migraine (1 paper, 2013). "A total of 32 SNPs showed marginal evidence for association to migraine and the best result was obtained for SNP rs9908234 in the nerve growth factor receptor -NGFR- gene but those results were not replicated in other cohorts." (PMID 23815568, 2013).
orofacial cleft (1 paper, 2021). A disorder of facial skeleton that is characterized by cleft lip and/or cleft palate that result in feeding, speech and hearing problems caused by failures during development. "Meanwhile, more numerous nerve growth factor receptor (NGFR) positive structures have been associated with orofacial clefts before mixed dentition." (PMID 34393631, 2021).
ovarian carcinoma (1 paper, 2024). A malignant neoplasm originating from the surface ovarian epithelium. "Previous studies have shown that NGFR is linked to WNT/β-catenin signalling and activates ovarian cancer tumour spread, while CYP1A1 was shown to be overexpressed in ovarian cancer clinical samples and to play a carcinogenic role." (PMID 38361045, 2024).
ovarian endometriosis (1 paper, 2025). A non-neoplastic disorder characterized by the growth of endometrial tissue in the ovaries. "Notably, ovarian endometriosis showed reduced NGFR expression (6.43, 6.34–6.56) relative to the other lesion types (p < 0.0001)." (PMID 41516088, 2025).
pancreatitis (1 paper, 2025). Inflammation of the pancreas. "Analysis of publicly available single-cell RNA sequencing (scRNA-seq) data from mice with acute experimental pancreatitis 40 revealed an enrichment of NGFR+ stromal cells during acute pancreatic injury, a condition associated with the emergence of ADM40." (PMID 41006303, 2025).
paraganglioma (1 paper, 2020). A benign or malignant neoplasm arising from paraganglia located along the sympathetic or parasympathetic nerves. "Fusion genes involving MAML3 (5%), BRAF (0.6%), NGFR (0.6%), and NF1 (0.6%) have been described as genetic disease drivers in a subset of paragangliomas." (PMID 32926213, 2020).
pilocytic astrocytoma (1 paper, 2023). Pilocytic astrocytoma is a rare subtype of low-grade glioma of the central nervous system characterized by a well circumscribed, often cystic, brain tumor with a discrete mural nodule and long, hair-like projections that extend from the neoplastic astrocytes. "We also examined more tumor‐related markers in PDOs at day 28, such as YAP1 and p75 NGFR for SHH MB and synaptophysin for pilocytic astrocytoma (Fig EV3E–H)." (PMID 38037472, 2023).
rheumatic diseases (1 paper, 2024). "Moreover, restriction of inflammation and upregulation of bone anabolism, as suggested by the role of NGFR, may implicate potential therapeutic options for RPOA or other bone-destructive rheumatic diseases." (PMID 38622181, 2024).
Tinnitus (1 paper, 2023). Tinnitus is an auditory perception that can be described as the experience of sound, in the ear or in the head, in the absence of external acoustic stimulation. "It is important to note that in the tinnitus group there were also close associations of BDNF to NGFR and of NGF to NTRK1." (PMID 37736859, 2023). "In summary, BDNF and NGF interact in tinnitus with NTRK1/NGFR in a competitive, modulatory manner influencing development, degeneration, and regeneration of neuronal and non-neuronal tissue." (PMID 37736859, 2023). "BDNF and NGF, in their interaction with NTRK1/NGFR, are involved in cell growth, survival, and regeneration, with the consequence of the changes in synaptic transmission connected with tinnitus." (PMID 37736859, 2023). "The key proteins of tinnitus differ from those assigned to PoS and AcouStim not only in the proteins themselves but also by the observation that the HDPs BDNF and NGF show HSIs with NGFR and NTRK1 at approximately the same level of interaction." (PMID 37736859, 2023).
vitiligo (1 paper, 2012). Generalized well circumscribed patches of leukoderma that are generally distributed over symmetric body locations and is due to autoimmune destruction of melanocytes. "Other studies revealed an increased number of nerve growth factor receptor-, calcitonin gene-related peptide- and protein gene product 9.5-positive nerve fibers in involved skin from vitiligo patients compared to healthy controls." (PMID 22500953, 2012).
tumor (256 papers, 2006 to 2026). "Together, these findings identify NGFR+ inflammation-associated stroma as a feature of lobular injury, contributing to the tumor microenvironment at the lobular tumor-pancreas interface." (PMID 41006303, 2025). "NGFR represents a benign-like stromal cell phenotype that disappears with the loss of liver cells (hepatocytes, reactive ductular cells) and tumor cell dominance." (PMID 37596278, 2023). "Our previous study indicated that NGFR acts as a tumor suppressor, and high expression is associated with better outcomes in patients receiving 5-FU-based adjuvant chemotherapy after surgery." (PMID 33996571, 2021). "In others words, what is the biochemical and molecular mechanism(s) underlying the essential role of NGFR in MICs’ stem-like phenotype and corresponding tumor growth?" (PMID 32686661, 2020). "Since gp100 is a recognized target for immune attack and NGFR is linked with tumor aggressiveness, this shift could lead to decreased immune surveillance and increased tumor malignancy." (PMID 40821768, 2025). "Together with our findings, these data support a model in which lobular injury, associated with tumor growth, induces a transient NGFR+/PDGFRα+ stromal phenotype in the peritumoral region, distinct from the established cancer-associated fibroblast subtypes characteristic of the desmoplastic stroma." (PMID 41006303, 2025). "Thus, NGFR-induced transcriptional changes within the tumor cells might be associated with evasion from recognition by innate immune cells." (PMID 36638181, 2023). "TrkA with the help of its downstream gene, Akt, leads the cell to survival fate, whereas NGFR is a cell surface receptor with multi‐functional role, which is implicated in injury, regeneration and development of nervous system, and also acts as a tumour suppressor." (PMID 33675128, 2021). "Within invaded lobules, NGFR abundance decreased as the distance between tumor cells and the intralobular tumor-exocrine interface increased." (PMID 41006303, 2025). "To highlight the potential for this approach to couple transgene expression to CAR activation, we first cocultured anti-Lewis Y CAR T cells engineered to express NGFR under the control of the NR4A2 promoter with Lewis Y+ tumor cells." (PMID 40610421, 2025). "The abrogation of PHOX1’s tumor-promoting effects by either NGFR knockdown or ERK1/2 inhibition provides compelling evidence for the functional importance of the PHOX1-NGFR-ERK1/2 signaling axis in GC progression." (PMID 41315175, 2025). "In iCCA cells and tumor tissues, NGFR mRNA level was considerably lower than in HIBEC and normal tissues." (PMID 40758712, 2025). "To confirm that antigen-mediated control of transgene expression was maintained in vivo, we adoptively transferred NR4A2/NGFR human CAR T cells into OVCAR-3 tumor bearing mice and observed tumor-site specific expression of NGFR." (PMID 40610421, 2025). "We followed tumor growth and noted that HK2 + TCR-T cells mediated a significant delay in tumor growth compared to the control group that was treated with NGFR + TCR-transduced T cells (n=6, p<0.01)." (PMID 40181966, 2025). "Cells in tumor cluster 3 had elevated NGFR expression, consistent with dedifferentiation into a neural crest-like state; these cells were mainly found in peritumoral, immune cell-dense regions." (PMID 41473281, 2025). "Immunoprecipitation with two membrane-bound proteins (CD99/MIC2, NGFR) allowed for reliable identification of tumour-derived sEVs." (PMID 39797974, 2025). "These occupied the extremum of the PCA state landscape and were uniformly populated by NGFR-high tumor cells with a vascular mimicry phenotype." (PMID 40667360, 2025).
tumor (continued). "In order to better understand the molecular regulation mechanism and biological functioning of NGF and NGFR in tumor tissues, GSEA was performed using the pan‐cancer approach." (PMID 38204220, 2024). "Tumor cells showed discrete and overlapping expression of MET, Ecad and MITF and were co-expressed with NGFR in a small subset of tumor cells." (PMID 38386085, 2024). "Consistently, PREX1 was downregulated in the NGF/NGFR low‐expression tumor tissues of HCC patients and also in the NGF and NGFR low‐expression co‐culture system." (PMID 38204220, 2024). "CSRI F4 transduced T cells contributed to a significant delay in tumor progression compared to NGFR F4 control cells (p=0.04)." (PMID 39512355, 2024). "NGF was observed to be co‐localized with NGFR on the membrane of the infiltrated T cells in the tumor tissues of HCC patients." (PMID 38204220, 2024). "The NGF secreted from the tumor cells communicated with the NGFR present on the membranes of T cells, which promoted T‐cell proliferation through the activation of the mitotic spindle signaling pathway." (PMID 38204220, 2024). "Nerve growth factor receptor is involved in signaling for tumor development and progression, with an important role in proliferation when overactivated." (PMID 39138146, 2024). "Consistently, the downregulation of NGF and NGFR in the tumor tissue of HCC patients was observed in the qRT‐PCR analysis and western blotting as well." (PMID 38204220, 2024). "NGF secreted by tumor cells interacts with NGFR present on the membranes of the infiltrated T cells, thereby promoting the proliferation through the activation of mitotic spindle signals." (PMID 38204220, 2024). "Together, these results suggested that the tumor cell‐secreted NGF was received specifically by the NGFR expressed in T cells, and NGF‐NGFR communication was inefficient in the tumor tissues of HCC patients." (PMID 38204220, 2024). "Two and a half weeks after tumor cell engraftment, mice were systemically treated with Dox to induce NGFR expression." (PMID 36638181, 2023). "Our conclusions are not biased because of artifacts of alloreactivity between cells from different human donors, because NGFR also confers protection from NK cell lysis to KIR-matched tumor cells." (PMID 36638181, 2023). "In recent studies, it has been discovered that certain tumor types show a high level of expression of neuron receptors such as Trks, NGFR, GFRα, L1CAM, NCAM, AchRs, AMPARs, NMDAR, and dopamine receptors." (PMID 37566075, 2023). "NGFR acts as a tumor suppressor in most cancers, leading to apoptosis and suppressing metastatic invasion." (PMID 36890467, 2023). "As we have found a notable role of lipid metabolism on attenuating NK cell function, it is plausible that aberrant fatty acid metabolism is a key molecular pathway in NGFR-induced NK cell evasion by inducing fundamental tumor cell remodeling." (PMID 36638181, 2023). "Tumor cells overexpressing NGFR were less killed by NK cells compared to control cells, an effect that was found at different effector to target cell ratios and consistent over different NK cell donors." (PMID 36638181, 2023). "Consistently, the nude mice study further confirmed that knockdown of LMO1 blocked tumor growth via NGFR-NF-kB axis." (PMID 35280742, 2022). "The depletion of NGFR suppresses human xenograft tumor growth and sensitizes cells to anti-cancer drugs." (PMID 35954323, 2022). "Specifically, in magenta, a subset of neural crest progenitor markers, such as NES, SOX10, ERBB3, and NGFR, were reported as highly expressed markers of Schwann cell progenitors and the signatures of stem-like tumor cells in NF1 tumors." (PMID 35741605, 2022). "The analysis of tumor biopsies collected before and on-treatment showed a decrease in MDA expression after treatment, with an enrichment of NGFR-expressing tumor cells in lesions collected during tumor progression." (PMID 35432344, 2022).
tumor (continued). "NGFR inhibits tumor cell proliferation, migration, and invasion by inducing apoptosis and G1 phase arrest, which is useful in inhibiting the onset and advancement of tumors." (PMID 36518255, 2022). "RNA-Seq data of patients treated with ICB revealed that the tumor-intrinsic NGFR signature predicts resistance to anti-PD-1 therapy before treatment and is further increased upon treatment." (PMID 35432344, 2022). "A NGFR+ subpopulation has also been identified as cancer initiating cells due to their capability of forming tumours and metastasising in mice compared to NGFR− subpopulations." (PMID 35740696, 2022). "Tumor cells express receptors such as tyrosine kinase receptor A (TrkA), TrkB, and NGF receptor (NGFR) that interact with these factors, leading to a downstream cascade that increases tumor proliferation." (PMID 36230740, 2022). "On the other hand, both TrkC (significant) and NGFR (non‐significant) genes were down‐regulated in the examined tumour samples." (PMID 33675128, 2021). "In our previous study, methylation of NGFR was observed in a substantial number of CRC cases and was associated with tumor progression and poor prognosis, whereas patients with high NGFR expression had better outcomes after 5-FU-based chemotherapy." (PMID 33996571, 2021). "We evaluated the effects of NGFR on tumor growth of CRC in mouse tumor models of NGFR- and vector-transfected HCT8 stable cell clones." (PMID 33996571, 2021). "p75NGFR or NGFR acts either as an oncogene or a tumour suppressor depending on the content of the cells." (PMID 33675128, 2021). "Increased in vivo efficacy by A2AR-knockdown CAR T cells was associated with increased expression of effector-related genes in tumor-infiltrating CD8+NGFR+ CAR T cells such as IFNγ, TNF, IRF4, and Granzyme B." (PMID 34050151, 2021). "On the other hand, opposite expression level of TrkC‐miR2‐5p‐GC related to the NGFR and TrkC genes in tumour tissue samples supports the functionality of this miRNA against NGFR and TrkC." (PMID 33675128, 2021). "NGFR overexpression promoting tumor migration and invasion has been observed in some metastatic cancers." (PMID 33996571, 2021). "On the other hand, NGFR has also been reported to suppress tumor growth and/or metastasis in prostate and bladder cancers." (PMID 33996571, 2021). "The neurotrophin receptors TRKA, TRKB, and P75/NGFR are expressed by malignant cells in many tumor types, where they inhibit key tumor suppressor mechanisms or directly promote cancer cell proliferation and invasiveness." (PMID 32155948, 2020). "We next evaluated the two most promising membrane-associated biomarkers (NGFR and CD99/MIC2) by IHC on primary tumor biopsies." (PMID 32821345, 2020). "Tumor cells harboring high cell surface expression of NGFR were much more resistant to MART-1 T cells than the NGFRlo population, as judged by a co-culture killing assay." (PMID 32770055, 2020). "CD271, also known as a neurotrophin receptor, nerve growth factor receptor, NGFR, or p75NTR, has been implicated in tumor growth." (PMID 33333727, 2020). "As detailed below, our studies elucidate a novel regulatory mechanism of p73 tumor suppressive activity, by which NGFR promotes p73 degradation through the CMA activity." (PMID 32285119, 2020). "To establish additional evidence that NGFR reduces p73 tumor suppressive activity, we utilized SK-MEL-147 cells with stable lentivirus expression of shNGFR or screener control, and overexpressed p73." (PMID 32285119, 2020). "Further, T cell cytokines such as TNF can induce NGFR expression on tumor cells leading to the acquisition of MART-1/gp100 T cell resistance." (PMID 32770055, 2020). "Out of nine genes differentially expressed in our study, five are included in the PI3K-AKT pathway, with three of them—FN1, NGFR, and THBS1—being associated with tumor progression." (PMID 32093414, 2020).